CCDC15 (coiled-coil domain containing 15)
Description:
Plays an important role in primary cilium assembly, maintenance, and length regulation. Interacts with centriole inner scaffold proteins to promote proper centriole size and integrity and assembly of functional cilia. Required for the recruitment of both the inner scaffold protein POC1B and the distal SFI1/CETN2 complex to centrioles.
Synonyms: FLJ13215
Tractability: Antibody: the Human Protein Atlas places it where antibodies can reach. PROTAC: ubiquitination databases record sites on it.
Gene: Protein-coding gene on chromosome 11 (124,954,095 to 125,041,649, forward strand). Ensembl gene ENSG00000149548.
Subcellular location: Cytoplasm, cytoskeleton, microtubule organizing center, centrosome; Cytoplasm, cytoskeleton, microtubule organizing center, centrosome, centriole; Cytoplasm, cytoskeleton, microtubule organizing center, centrosome, centriolar satellite
Subcellular location (Human Protein Atlas): Plasma membrane; Cytosol
Gene Ontology:
Biological process: cilium assembly; positive regulation of centriole elongation
Cellular component: centriole; centrosome; centriolar satellite
Genetic constraint (gnomAD): Loss-of-function variants: 69 observed, 66.66 expected, observed/expected ratio (o/e) 1.04, 90% interval 0.85 to 1.26. The upper end of that interval is the gene's LOEUF score, 1.26, which puts it in group 5 of 6, group 1 being the genes least tolerant of losing a copy. Missense variants: 806 observed, 797.43 expected, observed/expected ratio (o/e) 1.01, 90% interval 0.95 to 1.07. Synonymous variants: 238 observed, 282.75 expected, observed/expected ratio (o/e) 0.84, 90% interval 0.76 to 0.94.
Homologues: Orthologues: chimpanzee CCDC15 (99% identical), macaque CCDC15 (84% identical), rabbit CCDC15 (65% identical), pig CCDC15 (57% identical), dog CCDC15 (54% identical), mouse Ccdc15 (50% identical), guinea pig Ccdc15 (47% identical), rat Slc37a2 (46% identical), zebrafish ccdc15 (15% identical).
Diseases named in the same sentence as CCDC15 in open-access papers:
CCDC15 is named in the same sentence as 2 diseases in open-access papers, as found by Europe PMC text mining. Sharing a sentence is not in itself a finding about the gene and the disease. The quoted sentences say what the papers report.
cancer (3 papers, 2020 to 2023). A tumor composed of atypical neoplastic, often pleomorphic cells that invade other tissues. "In cancer cells, the protoplasts of CCDC15 (including exon 9) were oncogenic, and ADAR acted as a tumor inhibitor by influencing the growth of cancer cells through binding or catalytic editing, which makes the exon skip." (PMID 38203521, 2023). "To understand the functional importance of ADARs-mediated splicing changes in cancer, we examined the splicing pattern of CCDC15-ex9 and RELL2-ex3 in 33 matched pairs of primary ESCC and non-tumor (NT) samples." (PMID 32034135, 2020). "Many specific sites have been identified to play roles at different stages of cancer, such as tumor-promoting RES on the intronic region of the CCDC15, which affects the splicing process." (PMID 38203521, 2023).
tumor (3 papers, 2020 to 2023). "Moreover, CCDC15-ex9 inclusion were upregulated in 60% (20/33) of ESCC tumor samples, implying the potential oncogenic role of CCDC15-ex9 included isoform." (PMID 32034135, 2020). "All these data suggest that exon 9-included CCDC15 and exon 3-included RELL2 isoforms are oncogenic and tumor suppressive, respectively." (PMID 32034135, 2020).